RNASEH2A (ribonuclease H2 subunit A)
Diseases named in the same sentence as RNASEH2A in open-access papers (continued):
Sharing a sentence is not in itself a finding about the gene and the disease.
cancer (14 papers, 2013 to 2025). A tumor composed of atypical neoplastic, often pleomorphic cells that invade other tissues. "Together, these data suggest that RNaseH2A downregulation results in the production of cytoplasmic nucleotide ligands, inducing tumourigenic gene expression in cancer cells, which is likely linked to a poor prognosis." (PMID 36577784, 2022). "In the RNASEH2A immunohistochemical expression micro array, after deleting the tissue points shed during the experiment, the expression of RNASEH2A in the remaining 120 pairs of cancer and adjacent tissues was statistically analyzed." (PMID 35449547, 2022). "We also observed that a decline in RNaseH2A expression is associated with the accumulation of genomic DNA fragments in the cytoplasm and oncogenic SASP-like gene expression in cancer cells and organoids." (PMID 36577784, 2022). "We demonstrated that RNASEH2A gene amplifications have higher incidence in multiple cancer types when compared to deep deletions and normal diploid samples suggesting RNASEH2A as a target for cancer diagnosis and therapy." (PMID 33805806, 2021). "Via a series of bioinformatics approaches, we found that RNASEH2A is highly expressed in human proliferative tissues and many cancers." (PMID 33805806, 2021). "Recent studies have shown that the RNASEH2A subunit alone is highly expressed in certain cancer cell types." (PMID 33805806, 2021). "The analysis of copy number alterations of the RNASEH2A gene that we performed in our study further supports the role of RNASEH2A in cancer development." (PMID 33805806, 2021). "Another distinctive feature of RNASEH2A comes from examining its expression levels in cancer compared to normal tissues." (PMID 33805806, 2021). "To further explore the involvement of RNASEH2A in cancer, we examined the correlations between RNASEH2A and 39 additional genes in CCLE and TGCA Pan Cancer datasets." (PMID 33805806, 2021). "The high correlation of RNASEH2A expression with genes that play a role in cancer development and cell cycle progression validate our study, showing that RNASEH2A plays a role in cancer transformation and progression." (PMID 33805806, 2021). "The nucleotide degrading enzyme gene RNASEH2A (ribonuclease H2 subunit A) has been found to be overexpressed in cancers." (PMID 29843367, 2018). "In prostate cancer, a positive correlation between RNASEH2A expression and cancer aggressiveness has been reported." (PMID 29843367, 2018). "Upregulation of RNASEH2A in cancerous tissues compared with normal tissues was observed across cancer types, except for chromophobe kidney cancer (KICH)." (PMID 29843367, 2018). "We then hypothesised that RNaseH2A downregulation also induces inflammatory gene expression, which leads to the metastatic transformation of cancer." (PMID 36577784, 2022). "Thus, further analysis is important to determine the relationship between the biological function of RNaseH2A and malignant alterations in various cancer types." (PMID 36577784, 2022). "Taken together, these clinical findings are consistent with our model in which stress accumulation during cancer progression was assumed to drive R-loop accumulation, which is further attenuated by RNASEH2A induction to prevent R-loop–mediated DNA damage and apoptosis." (PMID 36923313, 2022). "Consistent with our findings, high expression of RNASEH2A may be involved in various types of cancers." (PMID 36923313, 2022). "Our findings underscore that RNASEH2A could serve as a biomarker for cancer diagnosis and a therapeutic target." (PMID 33805806, 2021). "RNASEH2A expression levels have been shown to be upregulated in transformed and cancer cells." (PMID 33805806, 2021). "Interestingly, RNASEH2A has also been reported to be upregulated in a variety of cancers, including breast, bladder, brain, prostate, head and neck cancers, seminomas, and leukemia." (PMID 29843367, 2018).
cancer (continued). "Pan-cancer analysis using TCGA tumor samples revealed a significant positive correlation between TRA16 and LSM4 (R = 0.63), as well as TRA16 and RNASEH2A (R = 0.6)." (PMID 40432923, 2025). "One of the common genes was ribonuclease H2 subunit A (RNASEH2A), a gene known for upregulation in cancers." (PMID 35401937, 2022). "At the same time, RNASEH2A and HENMT1 were positively correlated with the expression of clinical markers (MKI67) in cancer tissues." (PMID 35449547, 2022). "Additional bioinformatic analysis showed that RNASEH2A correlates with cancer progression and cell cycle related genes in Cancer Cell Line Encyclopedia (CCLE) and The Cancer Genome Atlas (TCGA) Pan Cancer datasets and supported our mass spectrometry findings." (PMID 33805806, 2021). "We detected the expression of the other six genes (MCM3, SPATS2, RRM2, NT5DC2, LRRC1, and RNASEH2A) in 30 pairs of HCC and para-carcinoma tissue by immunohistochemical staining assays." (PMID 32213663, 2020). "We first screened the messenger RNA (mRNA) expression of the nucleotide degrading enzyme genes TREX1, SAMHD1, RNASEH2A, RNASEH2B, and RNASEH2C in 14 cancer types using TCGA RNAseq data." (PMID 29843367, 2018). "Our results indicate that RNaseH2A downregulation provokes SASP through nucleotide ligand accumulation, which likely contributes to the pathological features of senescent, progeroid, and cancer cells." (PMID 36577784, 2022). "The correlation analysis uncovered a positive correlation of RNASEH2A with genes up-regulated in cancer and a negative correlation with genes that are instead down-regulated." (PMID 33805806, 2021). "A prognostication scoring system based on the expression levels of RNASEH2A-, CDK1-, and CD151-related genes could effectively predict the survival rate of RCC cancer patients (with a mean difference of four years in ccRCC)." (PMID 29843367, 2018). "Validation of the SDL relationships between RNASEH2A and CD151 in other cancer types is needed." (PMID 29843367, 2018). "Further bioinformatics investigation showed increased gene expression in different types of actively cycling cells and tissues, particularly in several cancers, supporting a biological role for RNASEH2A but not for the other two subunits of RNase H2 in cell proliferation." (PMID 33805806, 2021).
tumor (9 papers, 2018 to 2025). "Herein, we present the first evidence that the high expression of RNASEH2A promotes CRPC tumor growth." (PMID 36923313, 2022). "It was found that HENMT1 and RNASEH2A were positively correlated with the expression of tumor marker (MKI67)." (PMID 35449547, 2022). "Both in vitro and in vivo studies revealed that RNASEH2A promotes CRPC tumor growth and prevents DNA damage–mediated apoptosis." (PMID 36923313, 2022). "The expression of four proteins (MCM3, RRM2, NT5DC2, and RNASEH2A) was significantly upregulated in HCC tissues compared to that in non-tumor tissues." (PMID 32213663, 2020). "Our previous study on a Taiwanese colon cancer cohort showed that, in contrast to the downregulation of TREX1, SAMHD1, and RNASEH2C, RNASEH2A expression was found to be higher in tumor tissues when compared to paired normal parts." (PMID 29843367, 2018). "Finally, in order to explore the correlation between the markers predicted in this study and clinical tumor markers, the correlation between the experimental results of HENMT1, RNASEH2A and clinical tumor markers was analyzed." (PMID 35449547, 2022). "Collectively, we present a promising model in which excessive genomic instability due to R-loop accumulation could be suppressed by inducing RNASEH2A expression in CRPC to promote tumor growth." (PMID 36923313, 2022). "At the same time, compared with the diagnostic efficiency of simple tumor markers, HENMT1 and RNASEH2A combined with clinical markers (MKI67) have higher diagnostic efficiency and reduce the misdiagnosis and missed diagnosis rate of patients to a certain extent." (PMID 35449547, 2022). "Moreover, RNASEH2A overexpression accelerated tumor growth in vivo compared with the control." (PMID 36923313, 2022). "Furthermore, regulatory pathways that interact with RNASEH2A to determine the growth of tumor cells may exist." (PMID 29843367, 2018). "GEPIA database analysis showed that RNASEH2A and HENMT1 were positively correlated with the expression of tumor marker (MKI67)." (PMID 35449547, 2022). "RNASEH2A and HENMT1 are up-regulated in tumors, which can effectively distinguish normal tissues from tumor tissues." (PMID 35449547, 2022). "This suggests that RNASEH2A and CD151 have compensatory roles in promoting cell cycle progression and tumor growth." (PMID 29843367, 2018). "Interestingly, increased RNASEH2A and CD151 expression was observed in si-CDK1-treated ccRCC cell lines and were was found in RCC patients with a low tumor CDK1 level and bad clinical outcomes." (PMID 29843367, 2018). "To study the interactions among RNASEH2A, CDK1, and CD151 and their impact on tumor proliferation, we performed si-RNA knockdown studies on three ccRCC cell lines (786O, A704, KMRC3, all with VHL mutation) and one kidney urothelial carcinoma cell line (BFTC909, without VHL mutation)." (PMID 29843367, 2018). "CDK1 knockdown resulted in the upregulation of RNASEH2A and CD151 in all cell lines, however it did not significantly impair tumor proliferation (except for a mild effect on A704)." (PMID 29843367, 2018).
adenocarcinoma (1 paper, 2024). A common cancer characterized by the presence of malignant glandular cells. "The present results also exhibit that among the amplified genes, the following eight genes involved in the cell cycle were found to be amplified in more than 5% of HGSO adenocarcinoma patients: ATAD2, ASF1B, CCNE1, CDC20, CDCA8, RECQL4, RNASEH2A, and SMC4." (PMID 39199556, 2024).
RNASEH2A also shares sentences with these, for which no sentence is quoted: Encephalopathy (2 papers); autoimmune vasculitis (1); brain disease (1); breast invasive carcinoma (1); chilblain lupus (1); clear cell renal cell carcinoma (1); complement deficiencies (1); developmental delay (1); Intellectual disability (1); lung carcinoma (1); lupus (1); lymph node metastasis (1); melanoma (1); Pan (1); renal carcinoma (1); renal cell carcinoma (1); T-cell leukemia (1); type 1 interferonopathy (1).